HLA-DQB1 (major histocompatibility complex, class II, DQ beta 1)
Diseases named in the same sentence as HLA-DQB1 in open-access papers (continued):
Sharing a sentence is not in itself a finding about the gene and the disease.
infectious disease (4 papers, 2013 to 2024). A disorder directly resulting from the presence and activity of a microbial, viral, or parasitic agent in humans. "Further review of the ‘immune response’ GO cluster and genes within this category (CD1A, CD80, CD86, and HLA-DQB1) revealed related pathways which were in the same biological process associated with numerous autoimmune and infectious diseases." (PMID 38448477, 2024). "Genes regulated at 4 hours included CXCR5, HLA-DQB1, HLA-DOA, and were associated with the “antigen presentation, cellular compromise, infectious disease, respiratory disease” network (network score 46)." (PMID 23544148, 2013). "In addition, studies on MHC and infectious diseases have shown that MHC class II alleles; HLA-DRB1 and HLA-DQB1 have also been associated with more than 100 infectious diseases." (PMID 36161604, 2022).
digestive disease (1 paper, 2022). "Of note, HLA-DQB1 gene was previously shown to confer protection against cardiac or digestive disease in Brazilian chagasic patients." (PMID 35873155, 2022).
inflammation (1 paper, 2021). Aberrant reaction of the microcirculation characterized by movement of fluid and leukocytes from the blood into extravascular tissues. "LMAN1 has also been associated with coagulation, and both TNFAIP2 and HLA-DQB1 are associated with vascular inflammation." (PMID 33961016, 2021).
HLA-DQB1 also shares sentences with these, for which no sentence is quoted: gastric cancer (4 papers); autoimmune thyroid disease (3); colitis (3); Crohn disease (3); inflammatory bowel disease (3); psychiatric disorder (3); systemic sclerosis (3); adenocarcinoma (2); Arthritis (2); chronic kidney disease (2); dementia (2); Diabetic Nephropathy (2); hepatitis B (2); idiopathic hypersomnia (2); Löfgren syndrome (2); lung carcinoma (2); lung disease (2); mycosis fungoides (2); myositis (2); Nephropathy (2); neurological disease (2); non-Hodgkin lymphoma (2); primary adrenocortical insufficiency (2); tuberculosis (2); age-related macular degeneration (1); Alzheimer disease (1); angina pectoris (1); arboviral disease (1); autoimmune encephalitis (1); autoimmune pancreatitis (1).
A further 74 diseases each share a sentence with HLA-DQB1 in 1 paper.